IL25 (interleukin 25)
Diseases named in the same sentence as IL25 in open-access papers (continued):
Sharing a sentence is not in itself a finding about the gene and the disease.
asthma (continued). "IL-25 acts directly on bronchial epithelial cells (BECs) and circulating fibroblasts (CFs) in autocrine and paracrine-dependent manners, respectively, promoting airway remodeling and fibrosis in patients with asthma." (PMID 39060923, 2024). "Infection of immature mice with rhinovirus (RV) induces an asthma-like phenotype consisting of type 2 inflammation, mucous metaplasia, eosinophilic inflammation, and airway hyperresponsiveness that is dependent on IL-25 and type 2 innate lymphoid cells (ILC2s)." (PMID 38061015, 2024). "While TSLP, IL-25, and IL-33 are acknowledged as the key promoters of the T2-skewed inflammatory response in asthmatic airways, there is increasing evidence for the role of additional epithelial-derived cytokines in asthma pathology." (PMID 39457624, 2024). "Another subpopulation of CD4+ T helper cells known as Th25 can produce IL-25, which has been shown by numerous studies to play a crucial role in triggering an allergic response by connecting the innate and acquired immune responses in asthma." (PMID 38879568, 2024). "Although blockade to the IL-25 pathway is a validated therapeutic approach to asthma in pre-clinical studies, clinical application of targeting the IL-25 pathway is still lacking except a Phase I clinical trial of an IL-25 neutralizing antibody launched in 2023 (NCT05128409)." (PMID 39717777, 2024). "Additionally, it is important to note that there remain areas that require further research, including the precise role of IL-25 in severe asthma and investigating the long-term effects of IL-33 inhibitors." (PMID 39457624, 2024). "The application of upper airway TSLP and IL-25 measurement could therefore provide guidance on appropriate therapy in severe asthma; however, future studies are required to explore this possibility." (PMID 38999286, 2024). "In addition, we believe that the IL-25-(IL-17RB +)-CFs axis is not only a disease biomarker for asthma with FAL but also an important contributor to airway fibrosis and remodeling." (PMID 37635231, 2023). "Likewise, IL-25 is elevated in asthma and improves mitophagy and CCL-22 secretion in monocytes; moreover, inhibition of mitophagy by PINK1 knockdown reduces the production of CCL-22." (PMID 37181813, 2023). "Th2 lymphocytes induce pathological angiogenesis in asthma, via IL-25 production." (PMID 38143764, 2023). "The upregulation of IL-25 may lead to inflammatory diseases, including atopic dermatitis, psoriasis or asthma." (PMID 37005677, 2023). "Given that M1 macrophages are associated with airway neutrophilia and express IL-12 and IL-23, we hypothesize that IL-25 ameliorates airway neutrophilia via suppressing macrophage M1 polarization and the expression of IL-12 and IL-23 in asthma." (PMID 37898756, 2023). "First, we suggest that IL-25- and IL-17RB+-CFs may serve as specific disease markers in patients with asthma and FAL." (PMID 37635231, 2023). "We hypothesize that IL-25 ameliorates airway neutrophilia via inhibiting macrophage M1 polarization and the expression of IL-12 and IL-23 in asthma." (PMID 37898756, 2023). "Furthermore, they used an asthma mouse model to investigate more mechanisms of RV-induced IL-25 production in asthma." (PMID 36674744, 2023). "Our data suggest that the decreased expression of endogenous IL-25 in severe asthma or non-eosinophilic asthma is associated with increased expression of IL-12, IL-23, and M1 markers." (PMID 37898756, 2023). "RV infection of humans or mice upregulates Th2 inflammatory markers, including interleukin-13 (IL-13), interleukin-25 (IL-25), and interleukin-33 (IL-33), which may induce RV-driven exacerbation of asthma symptoms and drive remodeling." (PMID 37773065, 2023). "In our previous study, we have shown that IL-25 and CFs could predict a distinct asthma phenotype in FAL." (PMID 37635231, 2023).
asthma (continued). "Recent study demonstrated that allergen-initiated inflammation suppresses mTOR and induces autophagy in airway epithelial cells, resulting in the production of certain proallergic cytokines such as IL25, further promoting the type 2 response and eventually perpetuating airway inflammation in asthma." (PMID 35718777, 2022). "Eosinophils and basophils have been described as the major source of IL-25 in patients with asthma, but a wide range of cells produce and secrete IL-25, including also epithelial/endothelial cells, activated Th2 cells, alveolar macrophages, bone marrow-derived mast cells, and fibroblasts." (PMID 35406669, 2022). "TSLP, IL-33 and IL-25 are epithelial cell-derived cytokines that stimulate group 2 innate lymphoid cells (ILC2s) to release type 2 cytokines such as IL-5 and IL-13 and play an important role in asthma pathogenesis." (PMID 35292112, 2022). "In T2 asthma, the Th2 cytokines IL-4, IL-5, IL-9, IL-13, and IL-25, and the acute proinflammatory cytokines TNF-α, IL-1β, IL-6, and IL-8, subsequently lead to bronchial hyperresponsiveness (BHR), and plasma cells and antibody-producing cells secrete antibodies." (PMID 36430662, 2022). "On the other hand, IL-25 is involved in allergy, asthma and parasitic infections." (PMID 35056005, 2022). "Upregulation of IL25 may lead to inflammatory disorders such as atopic dermatitis, psoriasis, or asthma." (PMID 35359953, 2022). "In addition, asthmatic patients with higher IL-25 transcript levels were shown to have more severe disease, suggesting this cytokine is an important driver of asthma." (PMID 35406669, 2022). "In terms of an innate immunological barrier, epithelial cell activation and the release of epithelial cell cytokines, such as the alarmins, IL-25, IL-33, and thymic stromal lymphopoietin (TSLP), play a significant role in causing and exacerbating allergic diseases such as asthma." (PMID 36077310, 2022). "TSLP, IL-25 and IL-33, are designated as alarmin cytokines because their release from microbial, pollutant or allergen-perturbed epithelia heralds the onset of inflammatory responses in asthma." (PMID 36311787, 2022). "Since the seminal study by Fort and colleagues, in which the administration of IL-25 to mice was shown to elicit the production of T2 cytokines and induce gross eosinophilia, IL-25 has proven to be a main player in shaping allergy and asthma responses." (PMID 36311787, 2022). "Higher ATP levels are associated with elevated IL-25 and TSLP expression in type 2–high asthma." (PMID 33945508, 2021). "RV-infected asthmatic bronchial epithelial cells displayed an enhanced intrinsic capacity for IL-25 expression, which could contribute to asthma exacerbation." (PMID 35008429, 2021). "IL-25 is a Th2-like cytokine, and several studies have suggested its relationship with asthma." (PMID 35008429, 2021). "Oxidative stress has been identified as an elicitor of TSLP production, although this has not been proven in the skin, and IL-33 and IL-25, have been linked to it in other allergic diseases such as asthma." (PMID 34944487, 2021). "BALF (IL-25, IL-33, etc.), induced sputum (eosinophils, Th2 cells, etc.), and airway remodeling could all be used as a useful indicator for asthma diagnosis." (PMID 34136532, 2021). "Clinical trials of anti-IL-25 efficacy for asthma treatment are yet to be conducted." (PMID 34084159, 2021). "Furthermore, epithelial cell dysfunction acts as a major driver of asthma development, mainly because improper activation and production of IL-25 and TSLP from epithelial cells trigger allergy response." (PMID 33262394, 2020). "IL-25, also known as IL-17E, is evidenced to be involved in airway inflammation in asthma." (PMID 32448302, 2020). "Studies in both mice and humans suggest a role for IL-25 in asthma." (PMID 33255348, 2020). "Furthermore, epithelial cell-derived cytokines such as IL-33 and IL-25 (also known as alarmins) can play major role in the initiation of Th2-high asthma." (PMID 32477356, 2020).
asthma (continued). "Although the collected data supports an association between IL-25 and asthma, clinical trials using anti-IL-25 antibodies, as for TSLP and IL-33, have not yet been conducted." (PMID 33255348, 2020). "In light of the strong indication that they act as upstream drivers of T2-mediated disease, TSLP, IL-33, and IL-25 have attracted a lot of interest as potential therapeutic targets in asthma, and monoclonal antibodies targeting TSLP and IL-33 are currently under clinical evaluation." (PMID 33255348, 2020). "Based on the outcome of in vitro and in vivo studies, it is thought that RV may enhance Th2 cytokines via the expression of TSLP and IL-25 derived from airway epithelial cells; thus, exacerbating the lung disease in patients with asthma." (PMID 32637363, 2020). "In addition to IL-17, some cytokines, including thymic stromal lymphopoietin (TSLP), IL-33 and IL-25, are key factors for the development of allergic diseases, such as asthma and skin atopic dermatitis, that act by promoting Th2-type responses." (PMID 31805177, 2019). "We measured the levels of epithelial cytokines and epithelial damage markers in lung tissue in our asthma models and found that consistent with our findings for Th2 cytokines, IL-25 and -33 levels in BALF and lung tissues were increased in two OVA challenge groups as compared to each control group." (PMID 31823765, 2019). "IL-25 is an important mediator in RV-induced asthma exacerbations." (PMID 30345002, 2018). "Recognition of the powerful effects of IL-25, IL-33, and TSLP produced by respiratory epithelial cells is an important new element in understanding the potential for respiratory viruses to cause and/or exacerbate asthma." (PMID 29915592, 2018). "Since ILC2s have been detected in airway tissues, thus we hypothesize that the augmented Th2-cytokines in nasal tissue from CRS patients with asthma may be derived from sinonasal tract ILC2s in response to enhanced IL-25, IL-33 and TSLP release." (PMID 28199345, 2017). "Others have found increased systemic levels of IL-25 in subgroups of patients with TH2-high asthma." (PMID 28583446, 2017). "Instead, we supposed TH2-polarized T cells might be the main source of IL-25 to sustain the inflammation and influence the severity of asthma." (PMID 28481957, 2017). "Also, an elevated expression of IL-25 was observed in tissues of patients with asthma, atopic dermatitis, and chronic rhinosinusitis, indicating a possible link between the functions of IL-25 and the exacerbation of allergic disorders." (PMID 28912627, 2017). "Based on previous findings, we hypothesized that IL-25 in asthma could promote the activation of nuocytes, and then in turn induce a large amount of IL-5 and IL-13 to enhance Th2 cytokine responses." (PMID 27617447, 2016). "Th2-promoting cytokine IL-25 might contribute to bronchial mucosal vascular remodelling in asthma through its receptor expressed by vascular endothelial and vascular smooth muscle cells." (PMID 25889697, 2015). "In mice, overexpression or exogenous administration of IL-25 produces an asthma-like inflammatory response, including increased serum IgE production, blood eosinophilia and lung eosinophilic infiltrates, epithelial cell hyperplasia/hypertrophy, increased mucus secretion and airways hyperreactivity." (PMID 25889697, 2015). "In this model, we compared in parallel the effects of direct intranasal instillation of IL-25 with those of intranasal OVA administered to mice pre-sensitised to mount an IgE response to OVA by intraperitoneal sensitization (a “classical” murine asthma model)." (PMID 25889697, 2015). "The therapeutic benefits of inhibiting IL-25 in conditions, such as allergic lung inflammation, where airway remodeling is a key event, suggest that IL-25 is an important mediator of tissue regeneration and consequently fibrosis in conditions, such as asthma." (PMID 26635811, 2015).
asthma (continued). "A number of studies have shown that the epithelium of patients who have airway inflammatory diseases is structurally and functionally altered, and that bronchial epithelial cells that are isolated from patients with asthma or cystic fibrosis express increased levels of cytokines (IL-8, IL-25)." (PMID 26185364, 2015). "Plasma IL-25 did not associate with total IgE levels, previous exposure to peanut, severity of food allergic symptoms, or the presence of asthma and atopic dermatitis, nor did it correlate with organ specific symptoms during challenge." (PMID 24295226, 2013). "We reasoned that although ORMDL3 levels may not affect the production of IL-6 or IL-8 cytokines, perhaps they were impacting gene expression of other important immune genes, such as IL-33, IL-25 and TSLP, which have all been implicated in asthma pathogenesis." (PMID 23369242, 2013). "These novel findings suggest that blocking induction of a Th2 response during the neonatal period or later in childhood could be effective for primary prevention of asthma, and that IL-25 might play a crucial role in this process." (PMID 22574070, 2011). "Furthermore, we have recently provided convincing evidence that IL-25 is of crucial importance in the induction phase of childhood asthma." (PMID 22574070, 2011). "In addition, IL-25 mRNA is expressed in the lung in an animal model of asthma and neutralization of the produced IL-25 by soluble IL-25 receptor decreases antigen-induced eosinophil and CD4+ T cell recruitment into the airways." (PMID 18315837, 2008). "Studies carried out on severe asthma have identified specific characteristics linked to the T2-prevalent “component” of the disease: the involvement of ILC2 and of cytokines called alarmins (TSLP, IL-25, IL-23), as early effectors in response to the possible epithelial damage." (PMID 40469214, 2025). "According to reports, GSDMB may control the release of TSLP, IL-33, and IL-25, which are critical for the pathophysiology of asthma, by encouraging the infiltration of neutrophils and eosinophils in the inflamed airways; this is more pronounced in individuals with the T/C or T/T genotype." (PMID 39906448, 2025). "Other selected T2-high inflammation mediators related to eosinophils directly, IL-25 and eotaxin-1, are both critical players in the regulation of eosinophil recruitment and activation conditions characterized by eosinophilic inflammation such as asthma and eCOPD." (PMID 39766355, 2024). "Therefore, blunting IL-25 activity is an attractive target for asthma treatment." (PMID 39717777, 2024). "Together with other lung resident cells expressing IL-17RB, it is believed that IL-25 is highly contributed to the inflammation and lung damage via its direct action on lung endothelial cells, antigen presenting cells and Th2-related immune cells during asthma progression." (PMID 39717777, 2024). "Vitamin E and selenium have been shown to affect Th2 cytokines (IL-4, IL-5, and IL-13) as well as their upstream cytokines (IL-25 and IL-33), suggesting that they may be a beneficial treatment for the management of allergic diseases such as allergic rhinitis and asthma." (PMID 37513609, 2023). "With high expression of IL-25 receptors on eosinophils in asthma and the capacity of IL-25 to facilitate classical antigen presentation cell-dendritic cells (DCs) to initiate Th2 responses, we therefore asked whether IL-25 possesses the activity to augment eosinophils to initiate Th2 responses." (PMID 35615348, 2022). "In addition to asthma, the epithelial-derived alarmins IL-33, IL-25, and TSLP play important roles in the pathogenesis of other allergic diseases including allergic rhinitis, chronic rhinosinusitis, atopic dermatitis, food allergy, and allergic keratoconjunctivitis." (PMID 35406669, 2022).
asthma (continued). "However, a subgroup of patients with high bronchodilator reversibility demonstrated a clinically meaningful response to brodalumab, suggesting blockade of IL-25 may indeed be beneficial in some asthma patients." (PMID 35406669, 2022). "To determine if the reciprocal is true – IL-25 negatively regulates anti-viral responses - we used a potent anti-IL-25 mAb (LNR125) to determine if blocking IL-25 produced by BECs from patients with moderate to severe asthma augmented IFN production during RV infection." (PMID 35508632, 2022). "It was found that IL-25 and its functional receptor IL-17RB were significantly increased in the bronchial mucosa of asthmatic patients, and IL-25 was able to induce airway remodeling and angiogenesis in asthma and played an important role in pulmonary fibrosis." (PMID 35126394, 2022). "However, unlike IL-25 that promotes virus-linked asthma exacerbations by amplifying T2 responses, IL-33 can facilitate this process by hampering innate and adaptive Th1 and cytotoxic responses." (PMID 36311787, 2022). "In addition to TSLP, IL-33 and IL-25 may also represent further emerging targets for novel anti-asthma treatments." (PMID 34572294, 2021). "Therefore, TSLP, IL-33, and IL-25 represent suitable targets for add-on therapies of severe asthma." (PMID 34572294, 2021). "The evidence of IL-25-mediated Th2 cell differentiation, increase in production of IL-4, IL-5, and IL-13, elevated IgE and IgG levels, eosinophil infiltration, goblet cell hyperplasia and mucus hypersecretion, provided the proof for the role of IL-25 into asthma pathogenesis." (PMID 31355170, 2019). "Indeed, in a murine asthma model, it was shown that IL1α release by pulmonary epithelial cells induces allergic sensitization to inhaled house dust mite via autocrine release of Th2-driving cytokines IL25, IL33, and TSLP." (PMID 31427886, 2019). "However, this was a brief observation study for 4 weeks to minimize the risk of exacerbations and course variability of asthma that could have an impact on TSLP and IL-25 production." (PMID 31885750, 2019). "Thus, because IL-25-induced activation of ILC2s may contribute to human asthma and CRSwNP pathogenesis, IL-25 represents a potential therapeutic target." (PMID 28959799, 2017). "Furthermore, IL-25 and IL-33 levels were enhanced in asthma during innate immune response to allergens, and they play important roles at the onset of allergic inflammation in asthma." (PMID 29283409, 2017). "In another study, IL-22 attenuated IL-25 production by lung epithelial cells and inhibited antigen-induced eosinophilic airway inflammation, underscoring that IL-22 might exert protective effects in asthma." (PMID 28231834, 2017). "Moreover, IL-25 might be a potential clinical target for the treatment of airway remodeling in asthma, and its antibody maybe considered a good therapeutic candidate for the management of asthmatic airway inflammation." (PMID 27617447, 2016). "Therefore, our study indicates that IL-25 might be a potential clinical target for the treatment of airway remodeling in asthma." (PMID 27617447, 2016). "IL-25 (IL-17E), a distant member of the IL-17 family has been demonstrated to induce Th2-type immune responses, indicating that it may contribute to the pathogenesis of asthma and thereby this “vascular remodelling milieu”." (PMID 25889697, 2015). "Further, we have shown that, although a variety of Th2 cytokines as well as IL-25 have been implicated in causing remodelling changes in human and murine airways in asthma, only IL-25, and not IL-4, IL-5 or IL-13 is able directly to induce angiogenesis by human vascular endothelial cells." (PMID 25889697, 2015). "Thus, IL-25 may play an important role in enhancing allergic airway inflammation and is therefore a possible target for inhibition in the treatment of asthma." (PMID 18315837, 2008).